MORN1 (MORN repeat containing 1)
Synonyms: FLJ13941
Tractability: PROTAC: ubiquitination databases record sites on it.
Gene: Protein-coding gene on chromosome 1 (2,319,208 to 2,391,707, reverse strand). Ensembl gene ENSG00000116151.
Subcellular location (Human Protein Atlas): Mitochondria; Nucleoplasm; Nucleoli
Genetic constraint (gnomAD): Loss-of-function variants: 62 observed, 55.06 expected, observed/expected ratio (o/e) 1.13, 90% interval 0.92 to 1.39. The upper end of that interval is the gene's LOEUF score, 1.39, which puts it in group 5 of 6, group 1 being the genes least tolerant of losing a copy. Missense variants: 744 observed, 637.4 expected, observed/expected ratio (o/e) 1.17, 90% interval 1.1 to 1.24. Synonymous variants: 301 observed, 265.84 expected, observed/expected ratio (o/e) 1.13, 90% interval 1.03 to 1.25.
Homologues: Orthologues: chimpanzee MORN1 (98% identical), macaque MORN1 (93% identical), mouse Morn1 (66% identical), rat Morn1 (65% identical), dog MORN1 (62% identical), tropical clawed frog morn1 (44% identical), Drosophila melanogaster CG14490 (10% identical). Paralogues in human: RSPH10B (20% identical), RSPH10B2 (20% identical), ALS2CL (19% identical), RSPH1 (13% identical), MORN3 (12% identical), SETD7 (12% identical), MORN2 (8% identical).
Diseases named in the same sentence as MORN1 in open-access papers:
MORN1 is named in the same sentence as 3 diseases in open-access papers, as found by Europe PMC text mining. Sharing a sentence is not in itself a finding about the gene and the disease. The quoted sentences say what the papers report.
cystic kidney disease (1 paper, 2013). A congenital or acquired kidney disorder characterized by the presence of renal cysts. "These include MORN1 (FAP266) that has been implicated in basal body assembly in Toxoplasma, PIH1D1, which is part of the prefoldin complex and interacting proteins Reptin and Pontin have been implicated in cystic kidney disease in zebrafish and in Chlamydomonas." (PMID 23604077, 2013).
diabetes (1 paper, 2016). "Foremost, all four patients were affected by a homozygous, compound heterozygous mutations or de novo variant in a diabetes-relevant (CLTCL1 and PDZD2) or pancreatic expressed (MORN1 and ZNF330) gene." (PMID 28007035, 2016).
MORN1 also shares sentences with these, for which no sentence is quoted: oral squamous cell carcinoma (1 paper).